CTNNB1 (catenin beta 1)
Diseases named in the same sentence as CTNNB1 in open-access papers (continued):
Sharing a sentence is not in itself a finding about the gene and the disease.
asthma (6 papers, 2013 to 2025). "Regulating the expression of both genes along with the hub genes such as CTNNB1 could be important in the treatment of asthma across populations." (PMID 23829686, 2013). "Additionally, VDR expression was lower in patients with comorbid asthma (p = 0.036), and significantly reduced levels of OCLN (p = 0.006), CTNNB1 (p = 0.004), and FLG2 (p = 0.046) were observed in patients with total serum IgE ≥ 100 IU/mL." (PMID 40649943, 2025).
Ataxia (6 papers, 2016 to 2024). Ataxia refers to impaired coordination of voluntary muscle movement. "Interestingly, some cases corresponded to channelopathies associated with cognitive and motor delay, in which ataxia has also been described, including KCNC3, ITPR1, ATP1A3 and CTNNB1." (PMID 39048885, 2024). "These Sox2-creERT2::Ctnnb1(ex3)Fl/+ mice developed a marked failure to thrive until the age of postnatal day P21 with significant deficits in body size and body weight compared to controls and presented with general weakness and ataxia." (PMID 27902722, 2016). "However, sgCtnnb1-edited Tie2Cas9 mice did not develop petechial hemorrhages and ataxia (data not shown) as the adult inducible EC-restricted Ctnnb1 knockout mice." (PMID 35002515, 2022).
basal cell carcinoma (6 papers, 2013 to 2026). A carcinoma involving the basal cells. "Transcriptomic analysis identified activation of multiple oncogenic pathways, including WNT/CTNNB1, PI3K/AKT, basal cell carcinoma, sonic hedgehog signaling and epithelial-mesenchymal transition (EMT)." (PMID 42312452, 2026).
cholangiocarcinoma (6 papers, 2016 to 2025). A carcinoma that arises from the intrahepatic biliary tree (intrahepatic cholangiocarcinoma) or from the junction, or adjacent to the junction, of the right and left hepatic ducts (hilar cholangiocarcinoma). "We evaluated the frequency of TERT promoter and CTNNB1 mutations in 146 hepatocellular nodules including HCAs, LRNs, LDNs, HDNs, HCCs, and combined HCCs and cholangiocarcinomas." (PMID 27661004, 2016). "The expression of WNT1, APC was decreased in colon adenocarcinoma, and that of CTNNB1 was decreased in cholangiocarcinoma." (PMID 32764696, 2020). "We have analyzed TERT promoter and CTNNB1 gene mutations in 122 cases of hepatitis B (HBV) and hepatitis C (HCV) related HCCs, in 7 cases of cholangiocarcinoma (CC) and hepatocholangiocarcinoma (HCC-CC) as well as in autologous cirrhotic tissues." (PMID 27276713, 2016). "Although the Wnt pathway is known to be activated in bile-duct cancers, CTNNB1 mutation is not commonly reported in patients with cholangiocarcinoma and IPNB." (PMID 35382169, 2022). "Furthermore, correlation analysis using cholangiocarcinoma datasets from The Cancer Genome Atlas (TCGA-CHOL) showed that WNT pathway genes (AXIN2, CTNNB1, LEF1) positively correlated with TIC signature genes (KIT, SALL4, CD44, SOX2)." (PMID 39774471, 2025).
clear cell carcinoma (6 papers, 2018 to 2026). "In another clear-cell carcinoma, we describe a complex evolutionary history, including a spontaneous functional reversion of a CTNNB1 driver mutation in a secondary clone, which correlated with a switch in oncogenic expression programs." (PMID 42007974, 2026). "Endometrioid and clear cell carcinomas, frequently associated with endometriosis, are characterized by alterations of CTNNB1, PTEN, and POLE mutations, while clear cell carcinomas are characterized by ARID1A mutations." (PMID 35163166, 2022). "Both PIK3CA mutation and CTNNB1 mutation were also significantly associated with endometrioid and clear cell carcinoma." (PMID 34615547, 2021).
colon adenocarcinoma (6 papers, 2016 to 2024). "According to a GEPIA data source, CTNNB1 expression, which encodes β-catenin, is higher in colon adenocarcinoma (COAD) and rectal adenocarcinoma cells than in normal cells." (PMID 38891932, 2024). "DHA induced apoptosis in the human colon adenocarcinoma cell line HCT116, which carries an activating mutation of the β-catenin gene (CTNNB1), and SW480 cells with wild-type CTNNB1." (PMID 27527148, 2016).
endometrial tumors (6 papers, 2012 to 2025). "We observed here a marked dysregulation of cell differentiation processes in CTNNB1 mutated endometrial tumors." (PMID 41227323, 2025). "Namely, while survival analysis and immunohistochemistry are both consistent with literature data suggesting EMX2 as endometrial tumor suppressor, the EMX2high group of patients were found to have higher expression of CTNNB1 and FGFR2, two known oncogenes implicated in endometrial oncogenesis." (PMID 35361846, 2022). "Common genetic alterations in endometrial tumors include PTEN, PIK3CA, CTNNB1 (beta-catenin), and KRAS, all of which are related to metabolism." (PMID 31080560, 2019).
gastric adenocarcinoma (6 papers, 2017 to 2025). "One notable exception was the disruption of methylated DRACH sites in CTNNB1 being associated with a significant down-regulation of CTNNB1 transcript in the stomach adenocarcinoma cohort (TCGA–CESC)." (PMID 40271220, 2025). "Mutations of CTNNB1 encoding beta-catenin are closely correlated with multiple cancers including hepatocarcinoma, pancreatic cancer, colorectal cancer (CRC), gastroesophageal junction carcinomas and gastric adenocarcinoma." (PMID 34488905, 2021).
lymph node metastasis (6 papers, 2007 to 2022). "During the disease course, 66% (n = 25) of patients with a CTNNB1 mutation developed lymph node metastasis, 32% (n = 12) lung metastasis, 29% (n = 11) hepatic metastasis, 29% (n = 11) metastasis within the central nervous system (CNS), and 11% (n = 4) bone metastasis." (PMID 36077603, 2022). "Abnormal E-cadherin and CTNNB1 positively correlates with high grade ductal carcinomas, lymph node metastasis and poor survival." (PMID 17883861, 2007). "Furthermore, higher ER positivity was found in patients without lymph node metastases (p = 0.035), while higher PR positivity correlated with CTNNB1 mutated EC (p = 0.037) (Table A3 and Table A4)." (PMID 36358847, 2022). "Clinicopathological analysis showed that elevated expression of CTNNB1 in NSCLC was correlated with the tumor stage (P = 0.026), an increased incidence of death (P = 0.024), and lymph node metastasis (P = 0.007)." (PMID 34465343, 2021). "In contrast with recently published data, in our cohort CTNNB1 expression did not correlate with tumor differentiation or lymph node metastasis." (PMID 25633809, 2015).
meningioma (6 papers, 2012 to 2021). A generally slow growing tumor attached to the dura mater. "Atypical meningiomas that harbored a mutation in the exon or intron 3 of CTNNB1 showed a moderate signal of both forms of β-catenin in 75% of cases." (PMID 33915799, 2021). "Additionally, loss of miR-200a in meningiomas was shown to promote tumor growth by directly targeting beta-catenin (CTNNB1), but its role in BE remains unclear due to conflicting reports on the dysregulation of miR-200a." (PMID 29487725, 2018). "With respect to downstream gene sets of PI3K/Akt pathway, proliferation-promoted genes such as CTNNB1, CREB1, CREB5, and TCF7L2 were up-regulated in fibroblastic meningioma." (PMID 23285163, 2012).
parathyroid adenoma (6 papers, 2007 to 2023). "Additional mutational events occurring in low frequencies of parathyroid adenomas include activating CTNNB1 mutations, of which some have been reported as homozygous in small numbers, although not reproduced by others." (PMID 33269427, 2021). "DNA sequencing analysis detected the CTNNB1 stabilizing mutation S37A (TCT > GCT) in 6 out of the 104 (5.8%) analyzed parathyroid adenomas." (PMID 18541010, 2008). "Here we have determined the frequency and zygosity of mutations in exon 3 of CTNNB1, and β-catenin expression status in a large series of parathyroid adenomas of Swedish patients." (PMID 18541010, 2008). "We have found that a total of 9 out of 124 (7.3%) randomly selected parathyroid adenomas displayed the CTNNB1 stabilizing homozygous mutation S37A." (PMID 18541010, 2008). "The aim of the present study was to determine the frequency and zygosity of mutations in CTNNB1 exon 3, and β-catenin accumulation in a large series of parathyroid adenomas of Swedish patients." (PMID 18541010, 2008). "Taking our previous study into account, a total of 9 out of 124 (7.3%) randomly selected parathyroid adenomas displayed the CTNNB1 stabilizing mutation S37A." (PMID 18541010, 2008). "In addition to MEN1 and CCND1, other genes that participate in the development of parathyroid adenoma include those encoding cyclin-dependent kinase inhibitors, along with CTNNB1, EZH2, ZFX, GCM2, and CASR." (PMID 30832348, 2019). "study in 97 patients with sporadic parathyroid adenoma for mutations in exon 3 on CTNNB1 gene was negative for novel mutations except for S37A mutation which is already known from previous studies." (PMID 37223014, 2023). "DNA sequence analysis of 24 parathyroid adenomas from Japanese patients revealed no CTNNB1 mutations, and immunohistochemistry showed weak cytoplasmic β-catenin staining in 2 tumors." (PMID 18541010, 2008). "Stabilizing mutations of CTNNB1 have not been detected in parathyroid adenomas of patients from Japan and the United States." (PMID 18541010, 2008). "Furthermore, a recent study did not detect CTNNB1 exon 3 mutations in 97 sporadic parathyroid adenomas from patients who had undergone parathyroidectomy in the United States." (PMID 18541010, 2008). "Wnt/β-catenin/CTNNB1 signaling pathway is enrolled in tumorigenesis, but its role in parathyroid adenoma has not been yet elucidated." (PMID 37223014, 2023).
pituitary tumor (6 papers, 2013 to 2024). A benign or malignant neoplasm affecting the pituitary gland. "The p.S37C mutation accounts for only 2.8% of all 6939 CTNNB1 mutations analyzed in various mesenchymal and epithelial neoplasms, including hepatocellular, endometrial, ovarian, and pituitary tumors, according to COSMIC (April 2018)." (PMID 30206803, 2019). "According to the COSMIC database, CTNNB1 mutations have been detected at more than 10% frequency in neoplasms of pituitary (37%), soft tissue (36%), liver (22%), endometrium (18%), adrenal gland 13% and small intestine 12% (only entries with more than 100 sequenced samples):." (PMID 32155193, 2020). "Moreover, mutations in the third exon of the β-Catenin gene (CTNNB1), which encodes the GSK3-β binding site and is the degradation-targeting box of β-Catenin, are infrequent in pituitary tumors." (PMID 35928898, 2022).
renal cell carcinoma (6 papers, 2016 to 2022). "Additionally, VHL mutations indicate a diagnosis of SCA or a metastasis from a renal cell carcinoma, whereas CTNNB1 mutations a diagnosis of SPN." (PMID 35053560, 2022). "Depletion of CTNNB1 impaired the stem-like phenotype of renal cell carcinoma." (PMID 27917123, 2016). "CTNNB1 is a component of Wnt signaling pathway that is important in tumorigenesis and plays a key role in most cancers, acting as an oncogene; its knockdown inhibited cell proliferation, migration, and invasion and induced apoptosis in renal cell carcinoma (RCC)." (PMID 36500393, 2022).
uterine endometrioid carcinoma (6 papers, 2015 to 2025). "CTNNB1 gene variants were less frequent at 7% and are associated with increased risk of recurrence in grade 1–2 early-stage endometrial endometrioid adenocarcinoma." (PMID 37483495, 2023).
Alzheimer disease (5 papers, 2016 to 2025). A progressive, neurodegenerative disease characterized by loss of function and death of nerve cells in several areas of the brain leading to loss of cognitive function such as memory and language. "In mammalian models, these functions include stabilizing the binding of CTNNB1 and GSK3β, where Alzheimer disease causing mutations result in reduced stability of CTNNB1, and in endoplasmic reticulum (ER) calcium regulation." (PMID 30806144, 2019). "Moreover, abnormalities in PSEN151 and GLI252 functions, associated with the CTNNB1 gene are likely to be implicated in developing Alzheimer’s disease- and holoprosencephaly-like features in COVID-19." (PMID 36229517, 2022). "Interestingly, AKT1, MAPK8, BCL2L1, FOXO3, and CTNNB1 were not only significantly associated with pathogenic genes (APP, MAPT, and PSEN2) but also with longevity in Alzheimer’s Disease." (PMID 36620771, 2022). "In Alzheimer’s disease, specific transcription factors, such as MYC and CTNNB1, are altered in inhibitory neurons, leading to altered communication patterns between microglia and neurons." (PMID 40292254, 2025).
cholestasis (5 papers, 2016 to 2024). Impairment of the bile flow caused by obstruction within the liver, or outside the liver in the bile duct system. "Continuous β-catenin signaling due to somatic mutations in exon 3 of the Ctnnb1 gene is associated with different liver diseases including cancer and cholestasis." (PMID 29541410, 2018). "Activation of the Wnt/β-catenin pathway is frequently observed in HCC, and missense mutations in exon 3 of Ctnnb1 exhibit a histologically more aggressive phenotype and are associated with severe cholestasis, vascular invasion and recurrence of disease after orthotopic liver transplantation." (PMID 27895309, 2016). "CTNNB1-mutated HCC constitute a full-fledged subclass of HCC with distinct pathological features such as well-differentiated cells with low proliferation rate, association to cholestasis, metabolic alterations, immune exclusion and invasion." (PMID 39261716, 2024). "CTNNB1-mutated HCC has been proven to be a homogeneous subtype of non-proliferative tumors with well-differentiated characteristics such as an intact tumor capsule, cholestasis, microtrabecular, and pseudoglandular architectural patterns." (PMID 39434887, 2024).
clear cell ovarian cancer (5 papers, 2018 to 2024). "It has been reported that a patient with CTNNB1 mutation showed lower immune infiltration in HCC, and ARID1A mutation in ovarian clear cell carcinoma also has a role for immune inhibition, which is consistent with our result." (PMID 35124891, 2022). "For the study of genetically engineered mouse models, fortunately, both endometrioid and clear cell ovarian cancer have high frequency mutations in only a handful of genes: ARID1A, PIK3CA, CTNNB1, PTEN, and KRAS." (PMID 30087267, 2018). "ARID1A, PIK3CA, CTNNB1, PTEN, and KRAS are commonly mutated in both endometrioid and clear cell ovarian cancers from women." (PMID 30087267, 2018).
fibrous dysplasia (5 papers, 2017 to 2025). A genetic, non-inheritable disorder caused by osteoblastic differentiation defects that result in the replacement of bone marrow and trabecular bone by fibrous stroma and immature bone. "Alternatively, a mechanism of “selective apoptosis” of β-catenin mutated cells, similar to the supposed mechanism of “vanishing” GNAS mutations in long-standing fibrous dysplasia might be postulated to explain the CTNNB1 wild type status of a subset of osteomas." (PMID 34725446, 2022).
hyperopia (5 papers, 2017 to 2022). A refractive error in which rays of light entering the eye parallel to the optic axis are brought to a focus behind the retina, as a result of the eyeball being too short from front to back. "From over 40 previously reported patients with CTNNB1‐related neurodevelopmental disorder, many have had ocular anomalies including strabismus, hyperopia, and astigmatism." (PMID 33350591, 2021). "Also, a GNAS gene was associated with HM, TRAM1, CTNNB1, TENM3 and RUNX with myopia and/or refractive error, and EIF4B with low myopia/hyperopia in Europeans." (PMID 36685896, 2022). "All cases presented with CTNNB1-related facial dysmorphism (broad nasal tip, small alae nasi, long and flat philtrum, thin upper lip vermillion), and all but one case with eye abnormalities (strabismus = 5, hyperopia = 3, hypermetropia = 1, and esotropia = 1)." (PMID 36293418, 2022).
intestinal tumors (5 papers, 2014 to 2021). "For example, gene fusions involving R-spondin 1 occurring in 10% of intestinal tumor are mutually exclusive with active Wnt signaling caused by APC or CTNNB1 mutations." (PMID 31905853, 2019). "Apc-min (multiple intestinal neoplasia) mice have a mutated Apc gene which leads to a dysfunctional CTNNB1 destruction complex, overexpression of CTNNB1, and development of intestinal tumors." (PMID 25286307, 2014). "The discrepancy of R-spondin 1 dependence between tumorigenicity induced by the current method and previous GEMM relied on Apc depletion or CTNNB1 activation is supported by the mutual exclusion of R-spondin fusion and Apc or CTNNB1 mutation identified in human intestinal tumors." (PMID 31905853, 2019). "First we compared the effects of Pygo2 loss during the acute phase of intestinal tumor initiation induced by homozygous truncated Apc (Apc LOF; Pygo2+/+, +/− and −/−) and by heterozygous stabilized ß-catenin (Ctnnb1 GOF; Pygo2+/+, +/− and −/−)." (PMID 27811361, 2016). "Thus, also chemically induced intestinal tumors show a similar pattern of gene regulation in the context of Pygo2 knockout as seen in early stages of tumorigenesis induced by Apc LOF or Ctnnb1 GOF." (PMID 27811361, 2016).
oral cancer (5 papers, 2012 to 2024). "While recent work has shown CTNNB1 immunostaining levels to be significantly associated with lymph node status, survival outcomes, and different invasive stages for oral cancers, data regarding the association of CTNNB1 methylation status for this disease have not." (PMID 22645611, 2012). "It is worth noting that several of the functional partners including CTNNB1, SHH, FOXA2, and SOX2 have been reported to be involved in the progression of oral cancer or linked with the stem cell phenotype of oral cancer cells." (PMID 38304730, 2024). "Elevated expression and greater nuclear localization of CTNNB1 have been reported for oral cancer and a multitude of other cancer types." (PMID 22645611, 2012). "The genes CTNNB1 and MCM7 have been well studied for oral cancer but were not present in the databases which were taken initially for this study." (PMID 28559546, 2017).
Pancreatoblastoma (5 papers, 2018 to 2024). A rare malignant epithelial neoplasm arising from the pancreas. "This is consistent with previous reports of alterations in the genes for Wnt/β-catenin signaling, such as APC and CTNNB1, in pancreatoblastoma." (PMID 29535845, 2018). "Pancreatoblastoma is a rare malignant epithelial neoplasm of the pancreas that mainly occurs in children and involves abnormalities in the WNT/β-catenin pathway, such as CTNNB1 mutation." (PMID 34513702, 2021).